BDNF (brain derived neurotrophic factor)
Diseases named in the same sentence as BDNF in open-access papers (continued):
Sharing a sentence is not in itself a finding about the gene and the disease.
depression (continued). "And promoting the upregulation of BDNF level has emerged as an effective way to ease depression." (PMID 38259687, 2023). "The BDNF, COMT, and SLC6A4 genes were selected as they have been previously implicated in signaling pathways that are potentially disrupted in depression and can therefore be considered candidate genes for depression." (PMID 37754245, 2023). "The hypothesis was that plasma BDNF concentration will be decreased in patients with different forms of depression compared to healthy subjects, and that treatment (i.e., BLT) will increase plasma BDNF concentration in TRD patients." (PMID 37759825, 2023). "The effect of these changes on risk for post-stroke anxiety or depression may be exacerbated by social factors, leading to changes in the hypothalamic–pituitary–adrenal (HPA) axis that can perpetuate further BDNF decline." (PMID 37638348, 2023). "The kynurenine pathway is intertwined with numerous depression pathways, for example inflammation and immune cell activity, acute, chronic mild, and early-life stress, oxidative stress and mitochondrial function, and BDNF signaling." (PMID 36203007, 2023). "Moreover, neuroinflammation promotes the down-regulation of BDNF expression in depressed patients and depression model animals." (PMID 36829227, 2023). "This meta-analysis analytically reviewed recent studies concerning the potential associations between the brain-derived neurotrophic factor (BDNF) Val66Met polymorphism and susceptibility to major depressive disorder (MDD), with subgroup analyses for race and age." (PMID 37415688, 2023). "Our present findings might suggest that plasma BDNF is low in untreated patients with depression, normalized in remitted patients, but still low in those who did not respond to treatment." (PMID 37759825, 2023). "The increase of ACh levels in F rats suggests that a short-term fructose enriched diet may disrupt cholinergic signaling and predispose adolescents to altered states, such as anxiety disorders and depression, also corroborated by BDNF and dopamine reduction." (PMID 36394711, 2023). "Clinical evidence supporting the neurotrophic hypothesis of depression is based on postmortem studies that demonstrated that BDNF levels are decreased in the cerebral cortex of depressed and suicide subjects." (PMID 36978872, 2023). "Understanding the intricate relationship between serotonin and BDNF is crucial for advancing our knowledge of major depressive disorder, and recent studies have explored this connection, offering insights into potential therapeutic approaches for depression." (PMID 37631295, 2023). "In addition, TMS is known to induce long-lasting changes in neural networks through long-term potentiation and long-term depression mechanisms and by inducing neurotrophic factors increase in the brain (e.g., BDNF)." (PMID 37511869, 2023). "Therefore, the aim of this systematic review is to evaluate the role altered BDNF levels play in patients with CVD and those with depression in terms of increase in risk of depressive symptoms and that of CVD, respectively." (PMID 37895349, 2023). "These endotoxins can be translocated to the brain through the blood, and suppress serotonin and brain-derived neurotropic factor (BDNF) levels in the hippocampus, resulting in psychiatric disorders including depression and anxiety (DA) through neuroinflammation." (PMID 37299451, 2023). "Research has shown that signal transduction involving brain-derived neurotrophic factor (BDNF) plays a crucial role in synaptic plasticity in depression, and the downregulation of BDNF may contribute to neurotoxic effects." (PMID 38259274, 2023). "It has been reported that serum BDNF levels are reduced in patients with depression, as compared to healthy subjects, and antidepressants might increase it." (PMID 38107143, 2023). "Moreover, the authors pointed out that ECT has a more significant effect on the resolution of depression symptoms than on changes in BDNF concentration." (PMID 36831706, 2023).
depression (continued). "Additionally, BDNF levels can be altered by fecal transplants in the study of the effect of microbiota on depression." (PMID 37400661, 2023). "Peripheral BDNF decrease is noted in major depressive disorder patients." (PMID 37941931, 2023). "Furthermore, correlations between BDNF levels and anxiety or depression have been observed, with increasing evidence suggesting an association between low BDNF expression and suicidal behaviour." (PMID 37854466, 2023). "Lastly, comorbidities like depression and cardiac abnormalities can influence platelet activation, thus platelet reactivity, assessed by examining platelet factor 4 and or P‐selectin, should be examined in these patients when quantifying BDNF." (PMID 36722793, 2023). "The BDNF/TrkB/ERK/CREB signaling pathway could be one of the typical cellular signaling pathways affecting hippocampal neurogenesis for the anti-depression effect of NHQXW." (PMID 38273824, 2023). "Hesperidin and nobiletin, which are abundant in Shiikuwasha, reportedly exerted antidepressant effects and attenuated the reduction in hippocampal BDNF level in a mild traumatic brain injury- and chronic mild stress-induced rodent model of depression, respectively." (PMID 38082356, 2023). "Therefore, compounds that elevate BDNF level in the peripheral circulation potentially exhibit prophylactic and therapeutic effects against depression due to an increase in the level of BDNF transported to the brain." (PMID 38082356, 2023). "Besides, a substantial reduction in BDNF levels in rheumatoid arthritis patients with depression were detected, and the severity of depression is related to fatigue, poor BDNF expression, and serious state of rheumatoid arthritis." (PMID 37089920, 2023). "Indeed, low levels of BDNF were reported in the hippocampus of patients with depression and stressed animals." (PMID 36834565, 2023). "Enhancement in synaptic plasticity and BDNF expression might predict a unique mechanism for fast-acting anti-depression." (PMID 37305539, 2023). "In addition, Amuc_1100 alleviates antibiotic-induced anxiety and depression by modulating the BDNF/tropomyosin receptor kinase B (BDNF/TrkB) signaling pathway, thereby restoring the levels of BDNF and TrkB in the hippocampus and cortex." (PMID 37492530, 2023). "A decrease in BDNF levels has also been demonstrated in experimental models of depression." (PMID 37047638, 2023). "Additionally, it should be noted that some studies have shown that patients with depression have lower serum levels of BDNF." (PMID 36978923, 2023). "It is possible that changes in BDNF levels in depression might parallel a proinflammatory phenotype." (PMID 36178333, 2023). "Also, any changes in intestinal flora suppress hippocampal brain-derived neurotrophic factor expression in the neurons in the cortex and hippocampus leading to depression." (PMID 37565035, 2023). "It is also established that BDNF plays an important role in regulating anxiety and depression." (PMID 37371911, 2023). "Another study based on reserpine-induced depressive-like behaviors in rodents demonstrated that scopolamine attenuated the induced depression in mice partially by the regulation of the serotonin transporter, BDNF, and tryptophan hydroxylase 1 in the hippocampus and prefrontal cortex." (PMID 37631295, 2023). "Reduced depression-like behavior by elevating BDNF expression." (PMID 37242494, 2023). "Low BDNF levels decrease activation of cyclic AMP effector element binding protein (CREB), leading to down-regulation of miR-132, which affects neuroplasticity and causes depression." (PMID 38084332, 2023). "With computerized cognitive training improving mood and cognition and increasing serum BDNF levels in 6 weeks, it may serve as a safe and effective evidence-based alternative or adjuvant treatment for late-life depression." (PMID 38298930, 2023).
depression (continued). "The mechanism of the action of serum BDNF in the development of depression could be explained by the BDNF changes that occur in the brain immediately after stroke." (PMID 37895349, 2023). "However, the brain-derived neurotrophic factor (BDNF) has been reported among the underlying mechanisms of the association between suicidality and depression." (PMID 37891860, 2023). "Decreases in plasma and serum BDNF levels have been observed in patients with depression." (PMID 37631092, 2023). "In preclinical studies (i.e., the chronic social defeat stress model of depression), this molecule has proven antidepressant effects and also mitigated the decrease in hippocampal brain-derived neurotrophic factor (BDNF) signaling pathway, dendritic spine density, and neurogenesis induced by stress." (PMID 36986510, 2023). "This hypothesis is supported by extensive studies that reported that stress and depression led to lower serum levels of BDNF and decreased the expression of BDNF in brain regions that are involved in the regulation of mood and cognition." (PMID 37989582, 2023). "The aim of this pilot randomized controlled trial was to test the feasibility of a computerized cognitive training targeting executive dysfunction in late-life depression and to investigate its impact on mood, cognition, and brain-derived neurotrophic factor (BDNF) levels." (PMID 38298930, 2023). "Depression-like behavior was measured by a series of behavioral tests and neurobiochemical factors (5-HT, DA, and BDNF) and pro-inflammatory factors (IL-6 and TNF-α) were measured in brain tissues, combined with Nissl pathological analysis and determination of gut microorganisms." (PMID 37692389, 2023). "Increased activity of VTA DA neurons could increase BDNF release from their terminals in the NAc, which is necessary for depression-like symptoms in response to social stress." (PMID 33990773, 2023). "According to the generalized estimating equation analysis results, 8 single nucleotide polymorphisms (SNPs) belonging to the ANK3, BDNF, CACNA1C, and GRID1 genotypes were significantly correlated with depressive disorder (P < .001), with the majority belonging to the ANK3 and CACNA1C." (PMID 38012695, 2023). "In addition, the study pointed out the comorbidity between AN and depression and the fact that antidepressant treatment normalizes BDNF levels in patients with isolated depression, whereas this treatment has little or no efficacy in AN." (PMID 36831706, 2023). "Moreover, post-partum studies have demonstrated decreased levels of BDNF and BDNF receptor levels in the hippocampus of patients with depression and suicide victims." (PMID 37916205, 2023). "Current knowledge agrees that physical exercise may potentiate hormonal factors such as brain-derived neurotrophic factor (BDNF) to counteract with anxiety or depression disorders." (PMID 36658152, 2023). "Eight SNPs were associated with depressive disorder, namely rs142101917, rs191244436, and rs541490076 of the ANK3 genotype; rs193069165 of the BDNF genotype; rs116938681, rs188470158, and rs565998563 of the CACNA1C genotype; and rs558147168 of the GRID1 genotype." (PMID 38012695, 2023). "In addition, literature data suggest that the expression of the brain-derived neurotrophic factor (BDNF) is suppressed in depression and sleep disturbance." (PMID 36142262, 2022). "BDNF is essential for neurogenesis and the reduction in depression-like behaviors." (PMID 36668838, 2022). "This might be due to low levels of brain-derived neurotrophic factor and depression leading to hopelessness; it is a robust predictor of suicide." (PMID 35974397, 2022). "They determined that Gadd45b could play a role in neuronal remodeling activity-related neurogenesis in the hippocampus of adult rats, alleviating poststroke depression through the BDNF signaling pathway." (PMID 36311022, 2022).
depression (continued). "It would mean that reduction of BDNF in patients with OSA with depression symptoms may further exacerbate symptoms of this disease and hinder the therapeutic effects of antidepressants." (PMID 36498709, 2022). "Indeed, some of the drugs used to treat ASD and its accompanying comorbidities, such as depression, are known to affect BDNF levels." (PMID 35962006, 2022). "Apart from its beneficial effects on neurological conditions, vitamin D3 may diminish post-stroke depression and anxiety due to its stimulating effects on neurotransmitters and BDNF synthesis." (PMID 36358492, 2022). "However, the administration of BDNF to the NAc facilitated depression-like behavior, which demonstrated a network-dependent role of BDNF in mood regulation." (PMID 36430254, 2022). "BDNF is an example of a neurotrophin that has an impact on the pathophysiology of depression." (PMID 36014336, 2022). "In animal models, when stress induces depression, a downregulation of BDNF has been observed." (PMID 35886019, 2022). "This may indicate that there is a subgroup among patients with depression where working memory and BDNF levels are predictors of treatment processes." (PMID 36672535, 2022). "Finally, PCA revealed a positive correlation among LOX and BDNF and parameters determined in the anxiety tests, as between catalase activity and immobility time in the depression test." (PMID 36613269, 2022). "Low levels of BDNF signaling lead to hippocampal and cortical neural plasticity deficits, which are followed by neurodegenerative disorders, such as Alzheimer’s disease and major depression." (PMID 35237160, 2022). "Interestingly, BDNF emerged among the genes shared by depression and atherothrombosis, and it was well-connected to all the genes identified in both databases, namely, IL-1β, IL-6, IL-18, TNF, APOE, ACE, MTR, MTHFR genes." (PMID 35911513, 2022). "BDNF’s effect is related to the alteration of the gut microbial community, and it plays a vital role in neurodevelopment, plasticity, and maturation in adults, as well as in developing brains, to ameliorate depression." (PMID 36499295, 2022). "Interestingly, after the infection with SARS-CoV-2, the patients that developed symptoms such as depression and anxiety presented lower levels of BDNF compared to the controls." (PMID 35628626, 2022). "It is well acknowledged that there is a strong linkage between BDNF and depression." (PMID 36291673, 2022). "In a study conducted in the hippocampus of rats modeled after depression induced by maternal deprivation (MD) and chronic unpredictable stress, an increase in miR-16 expression was observed, followed by a down-regulation of BDNF." (PMID 36476595, 2022). "A significant increase in BDNF was found also in patients with depression." (PMID 35546921, 2022). "We also measured the amount of BDNF, a factor related to depression, in the mice hippocampi." (PMID 36299904, 2022). "In a relatively large community sample, it was found that plasma BDNF concentration was associated with depression-related personality traits in men, but not in women." (PMID 35815047, 2022). "BDNF plays an important role in the pathophysiological process of depression and anxiety." (PMID 35634463, 2022). "Furthermore, although depression is accompanied by dysfunction in the BDNF‐TrkB system and neurogenesis, many other pathological symptoms including neuroinflammation, the HPA axis and monoaminergic deficiency are also involved." (PMID 35848938, 2022). "In this study, we also observed lower levels of BDNF in mice with depression-like behaviors." (PMID 35572711, 2022). "Serum levels of E2 and BDNF were lower in the women with depression in comparison with controls." (PMID 35875795, 2022). "As for the limitation of the present study, we did not explore the role of microglia-derived BDNF in the pathogenesis of depression and whether microglia-derived BDNF plays a dominant role in the pathogenesis of depression." (PMID 36316319, 2022).
depression (continued). "Kyn pathway and BDNF expression are also connected in the context of depression." (PMID 35955633, 2022). "There are reports showing decreased blood levels of BDNF in patients with depression." (PMID 36291673, 2022). "Moreover, hippocampal reductions of BDNF have been also reported in animal models of depression and in the postmortem brain samples of depressed patients." (PMID 35911513, 2022). "Interestingly, the antidepressant effect of irisin seemed to be principally associated with two neurotrophins (BDNF and IGF-1), whose combined effect on depression reduction has already been reported in rats by i.c.v. irisin injections." (PMID 35886944, 2022). "Brain-derived neurotrophic factor (BDNF)-mediated signaling cascades are implicated in neuronal differentiation, synaptic plasticity and neurotransmission, claiming BDNF as a central molecule for various interventions for depression as well as other psychiatric disorders." (PMID 36572893, 2022). "Future research concerning the effects of endurance exercise on BDNF in post-stroke individuals might focus on other medical conditions (e.g., diabetes, depression, and obesity) and evaluate BDNF changes across disease conditions." (PMID 35743624, 2022). "An imbalance in 5-HT and BDNF signaling results in depression and anxiety disorders." (PMID 36499295, 2022). "There is increasing evidence that molecular mechanisms and cascades are involved in the pathology of depression such as low-level neurotrophic factors, in particular, brain-derived neurotrophic factor (BDNF), chronic inflammation, the hypothalamic-pituitary-adrenal (HPA) axis deregulation, etc.." (PMID 36291201, 2022). "It is assumed that HPAA deregulation, neuroinflammation and BDNF deficit in a number of brain regions may be common for the development of depression and AD." (PMID 35563389, 2022). "The antidepressant action of curcumin may be related to an increase in hippocampal BDNF expression, which directly correlates with the pathophysiology of depression." (PMID 36014776, 2022). "BDNF is involved in neuroplasticity and repair of stress-related neurological damage, it has been reported to be the most researched neurotrophic factor in the field of depression-related neurobiology." (PMID 36300881, 2022). "Microglial cytokine production may represent the main mechanism of BDNF suppression, in a similar fashion as demonstrated in major depression." (PMID 35344113, 2022). "BDNF is involved in the pathogenesis of many neuropsychiatric diseases and serum levels of BDNF are altered in many neuropsychiatric diseases, such as depression." (PMID 35009001, 2022). "Summarized, this study indicated that XYP could ameliorate hippocampal neuron damage in CUMS-induced depression model rats through acting on Cx43/GR/BDNF axis." (PMID 34984950, 2022). "BDNF is also important for synaptic plasticity and long-term memory and is known to play a key role in the pathophysiology of many psychiatric disorders, including depression, posttraumatic stress disorder, schizophrenia, and obsessive-compulsive disorder." (PMID 35875661, 2022). "Patients with schizophrenia and comorbid depression have decreased levels of BDNF and TrkB in serum and in the Hip, which may be accompanied by a decrease in the hippocampal volume." (PMID 35269761, 2022). "However, the high inter- and intra-individual variation in serum BDNF levels prevents the generalized use of BDNF as a biomarker of depression." (PMID 36142808, 2022). "Accordingly, a relatively recent meta-analysis found higher serum BDNF concentrations in patients with major depression disorder after 4 to 12 weeks of antidepressant treatment with a selective serotonin reuptake inhibitor and a selective noradrenaline recapture inhibitor." (PMID 35684488, 2022).